COL1A1 (collagen type I alpha 1 chain)
Diseases named in the same sentence as COL1A1 in open-access papers (continued):
Sharing a sentence is not in itself a finding about the gene and the disease.
breast carcinoma (continued). "Similarly to COL1A1, FN1 was also highly expressed in breast cancer and the advanced N1+ stage of breast cancer compared with their control groups." (PMID 30237810, 2018). "Oncomine analyses of COL1A1 and FN1 in different human breast cancer datasets suggest that these two genes may be promising targets for the future studies." (PMID 30237810, 2018). "This upregulation of COL1A1 in CAS is consistent with findings in human studies and matches the finding that collagen is progressively deposited during breast cancer development resulting in increased tissue stiffness as a classical fibrosis-type response of neoplasms." (PMID 28531107, 2017). "However, CS-E treatment of breast cancer cells plated on type 1 collagen-coated membranes was now unable to interfere with cell migration, demonstrating that an exogenous Collagen matrix could overcome the CS-E-mediated negative regulation of Col1a1 expression and cell migration." (PMID 25090092, 2014). "Furthermore, ligand‐receptor analysis showed that COL1A1/COL1A2‐SDC4/CD44 and MDK/NCL presented the highest communication probability, suggesting that these ligand‐receptor pairs are necessary for LN metastasis in breast cancer." (PMID 40492378, 2025). "Besides, COL1A1 expressed by ovarian cancer fibroblasts promoted migration and invasion of ovarian cancer cells and COL1A2 was identified as a hub node in the stromal module of breast cancer." (PMID 39695086, 2024). "Reclustering of the COL1A1-positive CAFs and removal of RGS5-positive pericytes resulted in four CAF subpopulations, of which the two major clusters (cluster 1 and 2) expressed iCAF and myCAF gene signatures, respectively, confirming the presence of iCAFs and myCAFs in human breast cancer." (PMID 36635273, 2023). "Its expression in breast cancer was found negatively correlated with the mRNA and protein expression of the DNA methyltransferase DNMT3A, which can alter global DNA methylation levels and, amongst others, result in increased collagen type I (COL1A1) promoter activity, contributing to high MD." (PMID 35954468, 2022). "To test whether COL1A1 and CHAD were driving the metastasis phenotype in human breast cancer, we used CRISPRi20 to create a pooled population of COL1A1 and CHAD knockdown in the Her2 amplified, COL1A1/CHAD amplified breast cancer line BT-474." (PMID 31332182, 2019). "Similarly, for early breast cancer, the best three k-gene discriminators are {GPR109B, PCOLCE2, PCSK5}, {PCSK5+COL10A1, FERMT2+SPINT2, MAOA+IGJ}, {COL1A1+PCSK5+TF, GPX3+COL1A1+SPINT2, GPX3+FAP+TMEM97}, and {RRM2+COL1A1+GPR109B+IGJ, RRM2+COL1A1+GPR109B+IGJ, RRM2+COL1A1+GPR109B+SPINT2}, respectively." (PMID 21060876, 2010). "However, no study on COL1A1 and FN1 associations with breast cancer has been reported." (PMID 30237810, 2018). "In this study, miR-129’s predicted regulation of COL1A1 underscores its potential role in extracellular matrix remodeling and tumor invasiveness, particularly in aggressive subtypes like TNBC and Non-luminal HER2+ breast cancer." (PMID 39850811, 2024). "Both CDK1 and COL1A1 are often amplified in breast cancer and high CDK1 mRNA expression significantly correlates with poor prognosis in breast cancer, with trend but not significant effects of both genes on survival of TNBC, possibly due to a smaller number of TNBC patients." (PMID 33911160, 2021).
gastric cancer (83 papers, 2007 to 2025). A primary or metastatic malignant neoplasm involving the stomach. "The alpha 1 chain of type I collagen is encoded by the COL1A1 gene and has been reported to be expressed in a variety of cancers, such as gastric cancer and glioma." (PMID 35711921, 2022). "Several previous studies have linked the expression of collagen type I alpha 1(COL1A1) and tumorigenesis in different cancers including human gastric cancer, lung cancer, and ovarian cancer." (PMID 36160115, 2022). "The previous study indicated that COL1A1 was associated with the gastric cancer and promoted cell migration and metastasis." (PMID 33506107, 2021). "Our current data confirmed that expression of COL1A1 was significantly elevated in gastric cancer tissues and is associated with tumor progression." (PMID 25860484, 2015). "Additionally, in gastric cancer, COL1A1 is highly expressed and associated with cancer cell invasion, metastasis, and poor prognosis." (PMID 37455825, 2023). "Notably, extremely high expression of COL1A1, which encodes type I collagen, was found in gastric cancer." (PMID 34319913, 2021). "COL1A1 has been identified to associate with gastric cancer invasion and metastasis." (PMID 25860484, 2015). "COL1A1 has been reported associated with more advanced tumor stage in 46 gastric carcinoma cases." (PMID 18302799, 2008). "By analyzing gene expression patterns through single-cell RNA sequencing, we found that several key genes, including SPARC, THBS2, COL1A1, and INHBA, are linked to poor prognosis in gastric cancer." (PMID 40075643, 2025). "The luciferase Assay indicated that miR-766-3p suppresses gastric cancer through directly targeting the 3'-UTR of COL1A1 mRNA and down-regulating the levels of COL1A1." (PMID 38230216, 2024). "Based on the confirmation of the data presented above, it is possible to conclude that COL1A1 is very significant to gastric cancer and is an essential target for miR-766-3p." (PMID 38230216, 2024). "COL1A1 knockdown can inhibit the progression of gastric cancer by regulating the PI3K/AKT signaling pathway." (PMID 39845977, 2024). "According to the findings, the high mRNA levels of COL1A1 have statically significant (P = 0.014) of OS in gastric cancer patients." (PMID 38230216, 2024). "Combining database, luciferase Assay and experimental validation, miR-766-3p can sponge COL1A1 and it plays the most important role in gastric cancer progression." (PMID 38230216, 2024). "According to Network Pharmacology analysis, COL12A1 and COL1A1 were the target genes of gastric cancer." (PMID 37700383, 2023). "Bioinformatics study of COL1A1 as a potential therapeutic target for gastric cancer, which is regulated by miR-129-5p61." (PMID 36755123, 2023). "RUNX2 has been shown to enhance NID1 signaling, and promote malignant progression in gastric cancer by regulating COL1A1, YAP1 and FN1 expression." (PMID 37256183, 2023). "The regulation of RUNX2 toward the extracellular matrix component collagen type I alpha 1 (COL1A1) was revealed in a gastric cancer study." (PMID 37108164, 2023). "Col1a1, fga, fgg, f2r, col3a1, and col1a2 are the important genes of this pathway, which are upregulated in gastric cancer." (PMID 35650297, 2022). "Studies have reported that COL1A1 not only has high expression in gastric cancer but also plays key roles in cancer cell invasion and metastasis." (PMID 35646104, 2022). "All second-generation gastric cancer sample-derived cells expressed COL1A1, and approximately 18% of cells expressed periostin, indicating that we obtained gastric cancer CAFs and that some CAFs were eCAFs." (PMID 34976204, 2022). "For example, miR-129-5p can regulate the expression of COL1A1 so as to promote the progression of gastric cancer, regulate YWHAB to affect the progression of lung cancer, and target ETV1 to inhibit prostate cancer proliferation." (PMID 36193492, 2022).
gastric cancer (continued). "High expression of COL1A1, COL3A1, COL5A1, FN1, and SPARC was significantly associated with poor survival in gastric cancer patients (p < 0.05)." (PMID 35739492, 2022). "collagen type I alpha 1 (COL1A1), a major element of the ECM and connective tissues, has been discovered to be actively associated with tumour size and depth of invasion in gastric cancer." (PMID 33954053, 2021). "Hub genes of COL1A1, COL4A1, COL12A1, and PDGFRB were overlapped in both PPI hub gene list and the turquoise module with significant association with the prognosis in gastric cancer." (PMID 35111208, 2021). "Our data showed that COL1A1 was highly expressed in lung cancer specimens (52.8%), which is in line with the previous reports on gastric cancer." (PMID 34475986, 2021). "To further confirm the pro-tumor effects of COL1A1 on gastric tumor progression, we used TCGA database to analyze the COL1A1 expression in gastric cancer patients with different stages and the overall survival." (PMID 34319913, 2021). "It has been reported that COL1A1 and COL1A2 are both overexpressed in gastric cancer, and a high COL1A1 and COL1A2 mRNA expression was suggested to be a prognostic factor predicting OS." (PMID 34283070, 2021). "Specifically, miR-129-5p restrains gastric cancer cell proliferation, migration, and invasion by suppressing COL1A1." (PMID 34660566, 2021). "In mouse models, COL1A1 was frequently upregulated in gastric cancer tissues; it increased cell proliferation, colony-forming efficiency, migration ability, and invasion ability, while it promoted the development of grafted tumors in mice." (PMID 34475986, 2021). "A recent study demonstrated that miR-129-5p suppressed gastric cancer cell proliferation, migration, and invasion by selectively inhibiting COL1A1." (PMID 34326879, 2021). "For example, it was reported that miR-129-5p inhibited cell viability of gastric cancer by downregulating COL1A1." (PMID 33506107, 2021). "MiR-129-5p was found to bind to the 3′UTR of COL1A1 mRNA in gastric cancer and hepatic stellate cells." (PMID 32075123, 2020). "Abnormal COL1A1 lead to increasing radioresistance in cervical cancer and had its potential prognostic value in gastric cancer." (PMID 31552163, 2019). "COL1A1 has been reported as a direct target of miR-218 in gastric cancer cells and human stellate cells." (PMID 30348200, 2018). "Previous studies have reported that COL1A1 is upregulated in gastric cancer, and plays important roles in cancer cell invasion and metastasis in this cancer." (PMID 28775672, 2017). "Given the progressive up regulation of COL1A1 in human liver and gastric cancers, we investigated how COL1A1 influences cellular process by genetically manipulating the expression of COL1A1 in CaSki and Hela cells." (PMID 28775672, 2017). "In the present study, we found that COL1A1 and COL1A2 were overexpressed in gastric cancer and potent prognostic factors by showing their associations with an adverse prognosis in gastric cancer patients." (PMID 27894325, 2016). "We note that key nodes such as COL1A1, COL1A2, JUN, MMP9, APOE, and FOS displayed strongest strength of interactions in the network, suggesting that these genes are key genes associated with other proteins in gastric cancer." (PMID 39044041, 2024). "In addition, we investigated the prognostic values of COL1A1 in gastric cancer patients based on the overall survival (OS) calculation." (PMID 38230216, 2024). "MiR-766-3p/COL1A1/PI3K/AKT may inhibit gastric cancer progression through suppressing ECM, metabolism, cell cycle progression and cell survival." (PMID 38230216, 2024). "By targeting COL1A1, down-regulation of the let-7i promotes gastric cancer invasion and metastasis." (PMID 36755123, 2023). "In addition, the host genes (CEACAM5 and COL1A1) of these circRNAs were the important therapeutic and prognostic biomarker for gastric cancer." (PMID 35359600, 2022).
gastric cancer (continued). "Moreover, COL1A1 was involved in the progression of a variety of cancer types, such as gastric cancer and pancreatic cancer." (PMID 35069551, 2021). "Moreover, knockdown of COL1A1 in gastric cancer cells curbed the proliferative, migratory, and invasive ability of cancer cells." (PMID 33969120, 2021). "Additionally, COL1A1 highly expressed in human breast and gastric cancer, while COL1A2 highly expressed in gastric cancer, and affected the prognosis." (PMID 33828526, 2021). "Moreover, COL1A1 has also been found to be positively related with the degree of invasion, metastasis, and advanced stages of gastric cancer." (PMID 32429941, 2020). "Several collagen genes were found to be overexpressed in gastric cancer and, among these, COL1A1 and COL4A1 were closely associated with overall survival of gastric cancer patients and could be regarded as risk factors for poor prognosis." (PMID 32046329, 2020). "Furthermore, COL1A1 can be silenced by MiR-129-5p which inhibits gastric cancer cell invasion and proliferation." (PMID 30568862, 2018). "It was found that expression of BGN (HR 1.9 [1.56–2.32], P = 1.3 × 10–10) was associated with worse overall survival (OS) for gastric cancer patients, as well as MMP2 (HR 1.78 [1.47–2.16], P = 2.6 × 10–9), COL1A1 (HR 1.49 [1.22–1.81], P = 8.2 × 10–5) and FN1 (HR 1.46 1.23–1.74], P = 1.3 × 10–5)." (PMID 29050278, 2017). "In addition, gastric cancer is usually a multi-step gradual process, and COL1A1 mRNA expression was significantly higher than that in normal epithelium but did not significantly change from premalignant to tumor specimens." (PMID 27894325, 2016). "We find that COL1A1 might have its potential as a monitoring factor to screen early gastric cancer, and COL1A1 and COL1A2 might predict poor clinical outcomes in gastric cancer patients." (PMID 27894325, 2016). "We demonstrate that COL1A1 and COLA2 are overexpressed in gastric cancer, high COL1A1 might be a monitoring factor for early gastric cancer, and high COL1A1 and COL1A2 mRNA expression could be prognostic factors predicting overall survival time." (PMID 27894325, 2016). "In GC, COL1A1 was upregulated and the enrichment analysis revealed that COL1A1 regulates PI3K/AKT signal pathway, and AKT is also highly expressed in gastric cancer." (PMID 38230216, 2024). "Preclinical studies have shown that COL1A1 may be a biomarker for poor prognosis in gastric cancer." (PMID 35842617, 2022). "Furthermore, it has been reported that in the osteosarcoma cells, COL1A1 and FN1 could be associated with gastric cancer prognosis." (PMID 35578666, 2022). "Moreover, let-7i-5p had been found to inhibit the proliferation and metastasis of colon cancer cells by targeting kallikrein-related peptidase 6 and significantly inhibit gastric cancer proliferation, invasion, and metastasis by targeting collagen type I alpha 1 chain." (PMID 33775245, 2021). "Then, we found that miR‐143‐3p is a shared miRNA between lncRNAs and mRNAs, including MAGI2‐AS3‐miR‐143‐3p‐COL1A1, NR2F1‐AS1‐miR‐143‐3pCOL1A1, and RP11‐999E24.3‐miR‐143‐3p‐COL1A1, and speculated that miR‐143‐3p and COL1A1 may be key genes involved in ceRNA pathways for gastric cancer." (PMID 31923354, 2020). "Furthermore, a subset of collagen genes was found to be differentially expressed in lesions of the human stomach and able to distinguish malignant from pre-malignant lesions, pinpointing these genes, in particular, COL11A1 and COL1A1, as biomarkers for early detection of gastric cancer." (PMID 32046329, 2020). "However, the clinical significance of COL1A1 and COL1A2 in gastric cancer remains unclear, and the expression of COL1A1 and COL1A2 in normal epithelium, premalignant, and tumor lesions of the stomach is rarely mentioned." (PMID 27894325, 2016). "For instance, COL1A1 promotes colorectal cancer metastasis by modulating the WNT/PCP pathway, and its upregulation, along with MFAP5, promotes EMT in gastric cancer." (PMID 40851082, 2025).
gastric cancer (continued). "Another in‐silico‐based study that analyzed multiple publicly available datasets identified collagen genes COL1A1, COL1A2, COL3A1, and COL5A1 as key CAF markers in gastric cancers." (PMID 39245631, 2025). "Among the prominent six genes highlighted in the protein-protein interaction network, higher expression levels of COL1A1, COL1A2, and APOE have also been confirmed to contribute to shorter survival in gastric cancer." (PMID 39044041, 2024). "A study related to gastric cancer indicated that MMP12 and COL1A1 collectively promote cancer progression." (PMID 39124881, 2024). "Altered expression of COL1A1 has been observed in numerous cancer types, including CRC, ovarian cancer (OV), gastric cancer (GC), melanoma, and glioblastoma, and promotes the proliferative and invasive ability of tumor cells." (PMID 38002057, 2023). "Similar results were also found in gastric cancer, in which the upregulated genes were COL1A2 and COL6A3 or COL6A3, COL3A1, and COL1A1." (PMID 38069077, 2023). "Previous studies have highlighted COL1A1, YAP1 and chemokine receptor CXCR4 as targets of RUNX2 that facilitate the in vitro invasion and metastatic potential of gastric cancer cells." (PMID 37256183, 2023). "C11_VWF were characterized by co‐expressing marker genes of fibroblasts (COL1A1, FAP, VIM, ACTA2) and endothelial cells (VWF, PECAM1, CLDN5, FLT1, RAMP2), which resembled a subgroup of cells undergoing an EMT transition in gastric cancer." (PMID 38115703, 2023). "Through GEPIA database, we found that COL1A1, COL4A1 and COL12A1 was differentially expressed in patients with gastric cancer, significantly suggesting a poor prognosis." (PMID 37700383, 2023). "Through GEPIA database, we found that COL1A1, COL4A1 and COL12A1 were differentially expressed in patients with gastric cancer, significantly suggesting a poor prognosis." (PMID 37700383, 2023). "In this study, we identified the six key CAF markers namely COL1A1, COL1A2, COL3A1, COL5A1, FN1, and SPARC in gastric cancer that can be used as predictors of CAF infiltration and prognostic biomarkers in gastric cancer." (PMID 35739492, 2022). "Several paired genes including (f2r, islr), (fn1, col1a1), (islr, col1a1), (islr, f2r), (pdgfrb, col1a1), (pdgfrb, f2r), and (vcan, col1a1) showed a positive correlation with each other, so that using antagonists against both of them could have a synergistic effect on the gastric cancer survival." (PMID 35650297, 2022). "There existed more positive expression results of COL1A1 and VCAN in gastric cancer tissues than in normal gastric tissues, indicating elevated protein levels of COL1A1 and VCAN in gastric cancer tissues." (PMID 36471693, 2022). "We identified ECM components COL1A1, COL1A2, COL3A1, COL5A1, FN1, and SPARC as the pivotal CAF markers in gastric cancer, which were separately reported as biomarkers of gastric cancer in different studies." (PMID 35739492, 2022). "Eight out of 38 upregulated genes in gastric cancer (ASPN, COL1A1, COL1A2, COL3A1, COL5A1, FAP, FN1, and SPARC) overlapped with the CAF markers list (circos plot on the left)." (PMID 35739492, 2022). "Among the six CAF markers, we identified COL1A1 and COL5A1 as the two markers which potentiated the poor prognostic impact of CAF infiltration most in gastric cancer." (PMID 35739492, 2022). "Our study revealed the COL1A1, COL1A2, COL3A1, COL5A1, FN1, and SPARC as the key CAF markers in gastric cancer." (PMID 35739492, 2022). "In gastric cancer tissues where protein expression was detected, the levels of the protein (BGN, VCAN, COL1A1 and TIMP1) were higher than in normal tissues." (PMID 34356118, 2021). "In this study, we also began with a DNA microarray to explore the expression of various genes in gastric cancer and found that two types of collagen were highly expressed in cancer tissues: COL7A1 and COL1A1." (PMID 34512204, 2021).